DBF4 (DBF4-CDC7 kinase regulatory subunit)
Diseases named in the same sentence as DBF4 in open-access papers (continued):
Sharing a sentence is not in itself a finding about the gene and the disease.
tumor (continued). "Therefore, we silenced Dbf4 expression in DPM tumor-forming cells using short-hairpin RNA and inoculated them orthotopically in athymic nu/nu mice." (PMID 35850776, 2022). "Compared to nontarget control DPM cells, Dbf4 loss significantly suppressed the tumor forming capacity by delaying tumor onset and reducing tumor growth rate." (PMID 35850776, 2022). "Therefore, these three key MVIRGs (DBF4, ARG2, and SLC16A3) are closely associated with the tumor and its prognosis, which also proves the correctness of choosing these three MVIRGs to establish a prognostic model to a certain extent." (PMID 34975331, 2022). "Specifically, the inhibition of DBF4, CCNA2, CCNB1, MCM6, CDC45, CHEK1, and CDC6 may be implicated in KCNQ1-mediated tumor suppression." (PMID 35216393, 2022). "Having confirmed the interaction of miR-30a and DBF4, next we performed rescue experiments to determine whether miR-30a functions as a tumor suppressor gene via regulation of DBF4." (PMID 34758839, 2021). "The important composition in tumor microenvironment, lactate, may be the primary factor that suppressed miR-30a to strengthen the expression of DBF4." (PMID 34758839, 2021). "Our study is the first time to identify DBF4 as a critical tumor suppressor in GC." (PMID 34758839, 2021). "Both DBF4 and CDC7 may be potential diagnostic and prognostic markers for HCC, and high expression of DDK members predicts a worse prognosis in patients with HCC, which may be associated with high tumor cell proliferation rate." (PMID 36609254, 2023). "Furthermore, our study identified the lactate-miR-30a-DBF4 axis as a crucial regulator of tumor progression and the tumor sensitivity to 5-Fu, which maybe serve useful for the development of novel therapeutic targets." (PMID 34758839, 2021). "To elucidate the potential mechanisms by which DBF4 exerts its effects in tumor cells, we compared the transcriptomes of HLF cells transfected with sh-NC and sh-DBF4." (PMID 38724606, 2024). "The differences in DBF4 and CDC7 expression in tumor tissues and adjacent normal tissues were analyzed." (PMID 36609254, 2023). "In this present study, we firstly comprehensively analyzed the expression of DBF4 and CDC7 in HCC patients, and found both of them were highly expressed in HCC tumor tissues." (PMID 36609254, 2023). "Dumbbell former 4 (DBF4) complexes with cell division cycle 7 (CDC7) to form DBF4-dependent kinase (DDK), playing instrumental roles in tumor cell survival, whereas its roles in HCC remain elusive." (PMID 37497004, 2023). "To investigate the expression of DDK complex members in HCC patients, we firstly sorted out the expression profile of DBF4 and CDC7 in TCGA dataset, and we found both DBF4 and CDC7 were significantly highly expressed in HCC tumor tissues." (PMID 36609254, 2023). "As shown, the expression of DBF4 and CDC7 was positively correlated with tumor grade and stage, and was much higher in advanced HCC patients with higher clinical stage and grade." (PMID 36609254, 2023). "Interestingly, the results observed that 5 hub genes were shared in the GEO and TCGA profiles, including SLC44A3, DBF4, NAPSA, ATP6V0A4, and CLDN4, which were closely associated with B cells, CD4+ T cells, CD8+ T cells, Macrophage, Neutrophil, and Dendritic cells to involve in tumor immunity." (PMID 36325324, 2022). "The results of the Wilcox test revealed that there was a significant correlation between the high expression of DBF4 (p<0.001), high expression of SLC16A3 (p<0.05), and tumor grade in HCC." (PMID 34975331, 2022). "High DBF4 expression was correlated with poor overall survival (OS), disease-specific survival (DSS), progression-free interval (PFI), disease-free interval (DFI), relapse-free interval (RFI) in majority of tumor types, particularly in patients with HCC." (PMID 38724606, 2024). "In addition, we used a Kaplan Meier plotter to investigate the relationship between DBF4 expression and RFS in different tumor patients." (PMID 38724606, 2024).
tumor (continued). "Further experimental validation revealed that DBF4 activates the ERBB signaling pathway, leading to alterations in the JNK/STAT, MAPK, and PI3K/AKT signaling pathways, thereby impacting the proliferative, migratory, and invasive abilities of tumor cells." (PMID 38724606, 2024). "Additionally, we explored the expression of DBF4 and CDC7 from the expression profiles from GSE25097, GSE54236 and GSE64041, in which both of them were higher expressed in HCC tumor tissues compared with adjacent normal tissues and minimum expressed in healthy normal livers." (PMID 36609254, 2023). "DBF4- depleted and negative control HCCLM3 and MHCC97H cells were subcutaneously injected into nude mice to measure tumor growth." (PMID 37497004, 2023).
infection (1 paper, 2021). The state of being infected such as from the introduction of a foreign agent such as serum, vaccine, antigenic substance or organism. "HIF1α, which is a key regulator of transcriptional signaling in hypoxic conditions, was induced following infection with either virus, as were HSP90B1 and DBF4, which are mediators of the unfolded protein response and cell cycle arrest, respectively." (PMID 33405202, 2021).
DBF4 also shares sentences with these, for which no sentence is quoted: colorectal cancer (2 papers); Oral Squamous Cell Carcinoma (2); colorectal tumors (1); diffuse large B-cell lymphoma (1); glioma (1); head and neck cancer (1); oral cancer (1); prostate carcinoma (1).